YTHDC1 (YTH N6-methyladenosine RNA binding protein C1)
Diseases named in the same sentence as YTHDC1 in open-access papers (continued):
Sharing a sentence is not in itself a finding about the gene and the disease.
periodontitis (2 papers, 2021 to 2022). An acute or chronic inflammatory process that affects the tissues that surround and support the teeth. "All 23 m6A regulators have remarkable differences in expression between 3 m6A modification patterns except for YTHDC1, validating the existence of diversity m6A modification patterns in periodontitis." (PMID 33724691, 2021).
Stroke (2 papers, 2020 to 2023). Sudden impairment of blood flow to a part of the brain due to occlusion or rupture of an artery to the brain. "After combining the mRNAs screened out via the LASSO, SVM, and RF algorithms, three diagnostic mRNAs (SPATA2, ZNF208, and YTHDC1) were identified for post-stroke depression." (PMID 37528851, 2023). "As stroke induced neuronal expression of YTHDC1, we examined whether knockdown of YTHDC1 influenced ischemic brain injury." (PMID 33188203, 2020).
testicular germ cell tumor (2 papers, 2020 to 2023). A germ cell tumor arising from the testis. "Some studies have shown that METTL3, ALKBH5, YTHDC1, YTHDF1, YTHDF2, and HNRNPC are the main m6A-related genes in type II testicular germ cell tumors." (PMID 32258108, 2020).
uveitis (2 papers, 2021 to 2022). An inflammatory process affecting a part of or the entire uvea. "A study on uveitis found that deletion of the m6A reader YTHDC1 enhances the M1 polarization of microglia and accelerates inflammation." (PMID 36212687, 2022). "In the present study, we first showed that the expression of the m6A reader YTHDC1 was downregulated in retinal microglia in two animal models of uveitis." (PMID 34975410, 2021). "Here, we analyzed the single-cell RNA sequencing data of retinal cells from mice with uveitis and found that the m6A-binding protein YTH domain-containing 1 (YTHDC1) was significantly downregulated in retinal microglia in the context of uveitis." (PMID 34975410, 2021). "Taken together, these results suggested that the m6A modification in retinal microglia in the context uveitis was changed during the inflammatory stage and that YTHDC1 was expressed at low levels in inflammatory microglia." (PMID 34975410, 2021). "In conclusion, our study elucidates the pivotal role of YTHDC1 in M1 microglial activation and suggests that the m6A modification may participate in the regulation of uveitis." (PMID 34975410, 2021). "We used high-throughput sequencing data to analyze the expression of m6A methyltransferases, demethylases and readers in retinal microglia in uveitis and found that YTHDC1 was expressed at significantly lower levels in microglia undergoing uveitis than in normal." (PMID 34975410, 2021). "Finally, the possibility that YTHDC1 may function in other roles in uveitis progression should be explored." (PMID 34975410, 2021).
Wilms tumor (2 papers, 2021 to 2025). An embryonal neoplasm characterized by the presence of epithelial, mesenchymal, and blastema components. "The combined effect of YTHDC1 polymorphisms significantly increases Wilms tumor susceptibility." (PMID 34897032, 2021). "Notably, certain single nucleotide polymorphisms (SNPs) that are present in m1A writers (TRMT6), erasers (FTO), and readers (YTHDC1 and YTHDF2) have been associated with the risk of Wilms tumour risk, emphasising the significant role of m1A modification regulators in Wilms tumour development." (PMID 41017026, 2025).
adenomyosis (1 paper, 2020). The growth of endometrial tissue inside the muscular wall of the uterine corpus. "From the analysis of the gene expression profile of GSE78851, we found that METTL3, ZC3H13, FTO, and YTHDC1 were all significantly decreased in the eutopic endometrium of adenomyosis patients versus controls." (PMID 32719721, 2020).
aortic aneurysm (1 paper, 2026). A ruptured aneurysm located in the wall of the proximal portion of the descending aorta proceeding from the arch of the aorta. "The cover highlights the Ythdc1‐p300‐Klf5 complex serving as a potential therapeutic strategy to improve Golgi dysfunction and aortic aneurysm." (PMID 41317401, 2026). "Similarly, we obtained the RNA‐seq data of m6A regulators Ythdc1 and Mettl3 from RNA‐seq public database (GEO number: GSE140947), and found that mRNA expression of Ythdc1 and Mettl3 is also upregulated in VSMCs of human aortic aneurysm sample." (PMID 41317401, 2026). "Targeting the Ythdc1‐p300‐Klf5 complex may serve as potential therapeutic strategy to improve Golgi dysfunction and aortic aneurysm." (PMID 41317401, 2026).
bile duct cancer (1 paper, 2025). "YTHDC1 silencing can suppress bile duct cancer cell proliferative, migratory, and invasive activity, lead to G2/M cell cycle arrest, and promote apoptotic death." (PMID 39994235, 2025).
brain ischemia (1 paper, 2020). Diminished or absent blood supply to the brain caused by obstruction (thrombosis or embolism) of an artery resulting in neurologic damage. "In combination with the previous study, we demonstrated that m6A reader YTHDC1 exerted a crucial role in neuronal survival after cerebral ischemia." (PMID 33188203, 2020). "Knockdown of YTHDC1 exacerbated ischemic brain injury and overexpression of YTHDC1 alleviated brain ischemia." (PMID 33188203, 2020). "To investigate the role of YTHDC1 after ischemia stroke, we first examined the expression pattern of the five known m6A “readers” in a rat model of cerebral ischemia/reperfusion (I/R)." (PMID 33188203, 2020).
carotid atherosclerosis (1 paper, 2024). A thickening and loss of elasticity of the walls of carotid arteries that occur with formation of atherosclerotic plaques. "Our previous findings have underscored the pivotal role of YTHDC1 in carotid atherosclerosis." (PMID 38168909, 2024).
diabetic retinopathy (1 paper, 2024). "The results further confirmed that overexpression of CDK6 reversed the protective effect of sh-YTHDC1 on diabetic retinopathy in vivo." (PMID 38978074, 2024). "Whereas, the molecular mechanism of YTHDC1 in diabetic retinopathy is still unclear." (PMID 38978074, 2024). "It suggested that the regulation of YTHDC1 in diabetic retinopathy may be related to the CDK6 methylation." (PMID 38978074, 2024). "We confirmed that YTHDC1 plays a key role in HG induced RVECs cells, suggesting that YTHDC1 may serve as a new drug therapeutic target for diabetic retinopathy." (PMID 38978074, 2024). "We hypothesized that YTHDC1 may be involved in the progression of high glucose induced diabetic retinopathy." (PMID 38978074, 2024). "Hence, a large number of basic studies need to focus on the regulatory role of YTHDC1 in diabetic retinopathy." (PMID 38978074, 2024). "Our study may reveal that YTHDC1 mediated methylation may be a novel strategy for the treatment of diabetic retinopathy." (PMID 38978074, 2024). "However, the molecular mechanism of YTHDC1-mediated methylation modification in diabetic retinopathy has not been reported." (PMID 38978074, 2024).
endometrial adenocarcinoma (1 paper, 2021). "The expression of YTHDF1, YTHDF2, and IGF2BP1/2 was increased in women with endometrial adenocarcinoma, whereas a reduction in YTHDC1 was detected." (PMID 34149936, 2021).
heart failure (1 paper, 2021). Inability of the heart to pump blood at an adequate rate to meet tissue metabolic requirements. "First, the Ythdc1‐cKO mice exhibit early DCM, which ultimately proceeds to heart failure and postnatal lethality." (PMID 34716659, 2021).
Hepatitis (1 paper, 2025). Inflammation of the liver. "In contrast, other m6A regulators, including METTL3, METTL14, WTAP, FTO, ALKBH5, YTHDC1, and YTHDC2, exhibited different protein expression patterns during ConA-induced hepatitis." (PMID 40092485, 2025).
lentivirus infection (1 paper, 2024). Virus diseases caused by the Lentivirus genus. "The lentivirus infection efficiency of shNAT10 and YTHDC1 was confirmed through western blotting analysis." (PMID 38233839, 2024).
metabolic syndrome (1 paper, 2025). A cluster of metabolic risk factors for CARDIOVASCULAR DISEASES and TYPE 2 DIABETES MELLITUS. "YTHDC1 protein levels were significantly lower in both diet-induced obese (DIO) and db/db mice compared to controls, suggesting that YTHDC1 in iBAT may play a role in regulating energy metabolism and metabolic syndrome." (PMID 40355558, 2025).
non-small cell lung carcinoma (1 paper, 2023). A group of at least three distinct histological types of lung cancer, including non-small cell squamous cell carcinoma, adenocarcinoma, and large cell carcinoma. "In non-small cell lung cancer (NSCLC), METTL3 mediates m6A modification of the circIGF2BP3 (hsa_circ_0079587) gene in a YTHDC1-m6A-dependent manner, which competitively upregulates PKP3 expression." (PMID 36960074, 2023).
osteomyelitis (1 paper, 2022). An acute or chronic inflammation of the bone and its structures due to infection with pyogenic bacteria. "Among the 6 m6A regulators, METTL3 and LRPPRC were highly expressed in subgroup A osteomyelitis, whereas YTHDC1 was highly expressed in gene cluster B osteomyelitis." (PMID 36544487, 2022). "Visualization of the results by boxplot and heatmap suggested that the 5 regulators were differentially expressed between the two m6A subtypes, with METTL3, CBLL1 and LRPPRC highly expressed in cluster A osteomyelitis, RBM15B and YTHDC1 highly expressed in cluster B osteomyelitis." (PMID 36544487, 2022). "In the m6A regulators-associated molecular subtypes, METTL3, CBLL1 and LRPPRC were significantly more highly expressed in subgroup A osteomyelitis than in subgroup B, while RBM15B and YTHDC1 expression were higher in subgroup A osteomyelitis." (PMID 36544487, 2022). "Based on the 6 significant m6A regulators with differential expression in the dataset, we further validated the expression of the 6 m6A regulators (METTL3, YTHDC1, YTHDF2, RBM15B, LRPPRC and CBLL1) in 10 osteomyelitis samples and 10 control samples by qRT‒PCR analysis." (PMID 36544487, 2022). "The qRT‒PCR results showed that the mRNA expression of METTL3, YTHDC1, RBM15B, LRPPRC and CBLL1 in osteomyelitis tissues was significantly increased, while that of YTHDF2 was significantly decreased (p < 0.05), which was consistent with the results of bioinformatics analysis." (PMID 36544487, 2022).
ovarian tumors (1 paper, 2023). "Consistently, our data demonstrated that YTHDC1 inhibits the growth and metastasis of ovarian tumors both in vivo and in vitro." (PMID 37781028, 2023).
pancreatic ductal adenocarcinoma (1 paper, 2024). An infiltrating adenocarcinoma that arises from the epithelial cells of the pancreas. "explored the YTHDC1/miR‐30d/RUNX1 pathway in pancreatic ductal adenocarcinoma, showing that YTHDC1 promotes miR‐30d biosynthesis, which targets RUNX1 to regulate SLC2A1 and HK1 expression, thereby inhibiting aerobic glycolysis." (PMID 39135292, 2024).
periosteal chondrosarcoma (1 paper, 2023). A chondrosarcoma arising from the surface of bone. "YTH Domain Containing 1 (YTHDC1) is a protein-coding gene, and diseases associated with the YTHDC1 gene include Wilms tumor 1 and periosteal chondrosarcoma." (PMID 37002245, 2023).
presbycusis (1 paper, 2025). Bilateral hearing loss caused by progressive degeneration of cochlear structures and central auditory pathways, typically associated with the aging process. "ALKBH5 and YTHDC1 emerge as promising biomarkers, presenting a potential pathway for diagnosing presbycusis." (PMID 40198960, 2025).
psoriasis (1 paper, 2024). An autoimmune condition characterized by red, well-delineated plaques with silvery scales that are usually on the extensor surfaces and scalp. "The roles of other genes, including ZC3H13, HNRNPC and YTHDC1, in psoriasis have not yet been explored." (PMID 38436011, 2024).
sarcopenia (1 paper, 2023). Progressive decline in muscle mass due to aging which results in decreased functional capacity of muscles. "It will also be interesting to determine whether YTHDC1 deregulation is implicated in muscle-related diseases such as aging-associated sarcopenia." (PMID 36892464, 2023).
synovial sarcoma (1 paper, 2024). "Among them, METTL3, YTHDC1, YTHDC2, RBMX, and ELAVL1 were significantly upregulated in synovial sarcoma tissue." (PMID 38549939, 2024).
thymoma (1 paper, 2023). A neoplasm arising from the epithelial cells of the thymus. "Similarly, the expression of YTHDC1 and YTHDF3 was negatively correlated with HS6ST2 in TGCT, but positively correlated with HS6ST2 in BLCA, COAD, UCEC, HNSC, PCPG, PRAD, SKCM, uterine carcinosarcoma (UCS), and thymoma (THYM)." (PMID 37932473, 2023).
urothelial carcinoma of the bladder (1 paper, 2025). "Integrative analysis of multimodal sequencing datasets provided detailed insights into the molecular mechanisms mediating YTHDC1-dependent phenotypes and identified SMAD6 as a key transcript involved in the invasiveness of urothelial carcinoma of the bladder." (PMID 39741187, 2025).
viral hepatitis (1 paper, 2025). An acute or chronic inflammation of the liver parenchyma caused by viruses. "Despite advances in understanding canonical m6A readers such as YTHDF1–3 and YTHDC1/2, the functions of noncanonical readers – such as IGF2BP1–3, HNRNPC, and HNRNPG remain largely unexplored in the context of viral hepatitis." (PMID 40793828, 2025).
tumor (105 papers, 2014 to 2026). "YTHDC1 has been linked to various physiological processes and to the development of different tumor types." (PMID 39741187, 2025). "By regulating the expression of genes involved in immune evasion, such as those encoding immune checkpoint molecules, YTHDC1 can modulate the immune microenvironment and affect the tumor’s susceptibility to immune-mediated destruction." (PMID 39911396, 2025). "YTHDC1 partially abrogated the inhibitory effect caused by NAT10 knockdown in tumor models in vivo, lentiviral overexpression of YTHDC1 partially restored the reduced stability of YTHDC1 caused by lentiviral depleting NAT10 at the cellular level." (PMID 38233839, 2024). "We observed tumour formation in all the animals (n = 12), with a significant decrease in size for those tumours deriving from YTHDC1-deficient cells, corroborating the in vitro experiments." (PMID 38951610, 2024). "Genes like APOBEC3B, APOBEC3C, and YTHDC1, highly expressed in tumor cells, were linked to tumor stemness and correlated with markers such as SOX2 and BM1." (PMID 39409886, 2024). "Conversely, a positive association was found between tumor purity and the expression levels of YTHDC1, EIF3A and CYP17A1 (average PCC = 0.42)." (PMID 38171932, 2023). "Specifically, the increased YTHDC1 expression was associated with the following clinical characteristics of HNSCC patients: higher tumor grade, positive HPV presentation, and increased lymph node metastasis." (PMID 36411870, 2022). "The higher rate of mutations of YTHDC1 in tumor cells suggests a potentially abnormal function of m1A." (PMID 33779693, 2021). "While YTHDF2, RBM15, ZC3H13, METTL3, HNRNPC, YTHDC1 with m6a modifications had higher expression in the low risk group, indicating that they might be tumor suppressors." (PMID 36199800, 2022). "However, after adjusted to age, molecular classification, grade, tumor size, lymph node status, endocrine treated, and chemotherapy treated, only YTHDC1, FMR1, IGF2BP1 and WTAP showed a significant association." (PMID 34141492, 2021). "TRMT10C (‘writer’), YTHDF1 (‘reader’) and YTHDC1 (‘reader’) genes had the greatest number of mutations, with missense mutations potentially leading to impaired function, affecting m1A signaling in cells and causing physiological disorder in tumour cells." (PMID 32934298, 2020). "METTL3/14, YTHDF2/YTHDC1 proteins work to maintain the activity of oncogenes, inhibit tumor suppressor genes, and drive cancer development by regulating m6A RNA modification." (PMID 41446042, 2025). "In ovarian cancer, for example, YTHDC1 has been found to act as a tumor suppressor in a m6A-dependent manner through its binding and stabilization of PIK3R1 mRNA21." (PMID 39741187, 2025). "On the other, DDX5 cooperates with the m6A reader YTHDC1 to drive the biogenesis of a tumor-specific subset of circular RNAs (circRNAs), which further contribute to RMS pathogenesis." (PMID 40950397, 2025). "piR-26441 suppresses mitochondrial oxidative phosphorylation and proliferative capacity in ovarian carcinoma cells via YTHDC1-mediated m6A modification, thereby attenuating tumor metabolic adaptation and growth." (PMID 40986143, 2025). "Collectively, these findings suggest that YTHDC1 downregulation promotes tumor invasiveness in UCB by facilitating p-EMT." (PMID 39741187, 2025). "Following sampling, the mouse tumor weights of kd-YTHDC1 group notably decreased relative to kd-NC group." (PMID 38573528, 2024). "To validate this finding in a more physiological environment, we injected YTHDC1-knockdown or scrambled siRNA control A549 cells into immunosuppressed mice to allow tumour formation." (PMID 38951610, 2024). "YTHDC1 is a nuclear m6A reader, that plays a critical role in tumor development by a m6A-dependent manner." (PMID 38233839, 2024).